GPX2 (glutathione peroxidase 2)
Diseases named in the same sentence as GPX2 in open-access papers (continued):
Sharing a sentence is not in itself a finding about the gene and the disease.
bladder cancer (5 papers, 2018 to 2024). "Our findings suggest that up-regulation of GPX2 is in fact associated with bladder cancer development via its role in regulation of apoptosis and oxidative stress." (PMID 29662611, 2018). "Recently, the prognostic significance of GPX2 in human malignancies was reported, and only one report has described that low expression level of GPX2 is associated with poorer prognosis in bladder cancer." (PMID 29662611, 2018). "In this report, we extended our investigations based on these previous findings, and elucidated the role and prognostic significance of GPX2 in bladder cancer." (PMID 29662611, 2018). "Herein, we elucidated the molecular mechanisms and therapeutic potential of glutathione peroxidase 2 (GPX2) in bladder cancer." (PMID 29662611, 2018). "Thus, it has been shown that increased GPx-2 is related to the promotion, growth, and metastasis of colorectal, hepatocellular, and bladder cancers." (PMID 37761814, 2023). "From our findings of the role of GPX2 in bladder cancer, we propose that GPX2 may serve as a prognostic biomarker for pure UC patients." (PMID 29662611, 2018). "In addition, in vivo analyses of the BBN-induced rat bladder cancer model following transplantation of BC31 cells with Gpx2 knock-down showed that tumor growth, SqD, angiogenesis were all suppressed, and caused the induction of apoptosis." (PMID 29662611, 2018). "Our findings demonstrated that GPX2 plays an important role in bladder carcinogenesis through the regulation of apoptosis against intracellular ROS, and may be considered as a novel biomarker or therapeutic target in bladder cancer." (PMID 29662611, 2018).
ileocolitis (5 papers, 2010 to 2024). Ileocolitis or ileal Crohn's is the most common type of Crohn's disease. "Genetic background affects susceptibility to ileocolitis in mice deficient in two intracellular glutathione peroxidases, GPx1 and GPx2." (PMID 20976020, 2010). "In the mouse, combined deficiency of GPX1 and GPX2 pre-disposes to ileocolitis." (PMID 39536393, 2024). "Notwithstanding the limitations related to potential linkage disequilibrium and difficulties in meeting assumptions of Mendelian randomization, in a specific Gpx1-null and Gpx2-null murine model (B6), the development of ileocolitis was facilitated." (PMID 39202524, 2024). "Previous analyses have shown that a double knockout of GPx1 and GPx2 results in spontaneous ileocolitis." (PMID 23977205, 2013). "This is consistent with the spontaneous ileocolitis and intestinal cancer in GPx1/GPx2 double-knockout mice." (PMID 23977205, 2013). "In addition, GPx1/GPx2 double KO mice spontaneously developed an ileocolitis." (PMID 31765890, 2020). "In GPx1-GPx2 double KO animals, only the re-introduction of GPx2 but not of GPx1 was able to rescue the phenotype of spontaneous ileocolitis and subsequent intestinal cancer formation." (PMID 31765890, 2020).
lung squamous cell carcinoma (5 papers, 2020 to 2024). "YAP promoted ROS accumulation through the downregulation of GPX2, thus triggering cell growth inhibition in lung squamous cell carcinoma." (PMID 38914724, 2024). "Similarly, YAP activation leads to excessive accumulation of reactive oxygen species by downregulating the antioxidant enzyme glutathione peroxidase 2 (GPX2), inhibiting the growth of lung squamous cell carcinoma." (PMID 38566194, 2024). "In addition, the increase in GPx2-mediated ROS levels could suppress tumor development via the Hippo pathway in lung squamous cell carcinoma." (PMID 37138031, 2023). "CAT, ENO1, NQO1, P4HB, and PDIA6 were unique to LUAD, while CAV1, GAPDH, GPX2, GPX3, and PDIA4 exhibited consistent trends in differential expression in both LUAD and lung squamous cell cancer, significant prognostic survival prediction (p<0.05), and excellent classification effectiveness." (PMID 37955007, 2023). "The findings suggest that YAP has a tumor-suppressor function through downregulating GPX2 expression in a DNp63-dependent manner, and more studies focus on the regulation of ROS by YAP are needed to improve precision medicine for the treatment of lung squamous cell carcinoma." (PMID 32466572, 2020).
esophageal squamous cell carcinoma (4 papers, 2016 to 2025). Esophageal squamous cell carcinoma (ESCC) is a type of esophageal carcinoma (EC) that can affect any part of the esophagus, but is usually located in the upper or middle third. "It has previously been shown that GPX2 protein is overexpressed in neoplastic transformation of squamous epithelial cells, Barrett’s esophagus, and esophageal squamous cell carcinoma." (PMID 29662611, 2018). "Recently, it has been suggested that GPX2 might be an important predictor for the prognosis of esophageal squamous cell carcinoma and a potential target for the intervention and treatment of this disease." (PMID 32327612, 2020).
intestinal cancer (4 papers, 2012 to 2021). "Mice in which both GPx1 and GPx2 had been knocked out developed ileocolitis and later intestinal cancer." (PMID 22654914, 2012). "GPX2 overexpression is associated with increased cancer cell proliferation through WNT signaling, resistance to apoptosis by reducing ROS, and enhanced growth in breast and intestinal cancers." (PMID 24280356, 2013). "Activation of the GPx2 promoter by β-catenin, which is the key mediator in the Wnt pathway and constitutively active in most of intestinal cancers, can again be interpreted controversially, either as an attempt to counteract carcinogenesis or to sustain cancer cell growth." (PMID 22654914, 2012).
melanoma (4 papers, 2022 to 2026). A malignant, usually aggressive tumor composed of atypical, neoplastic melanocytes. "Clinically important cancer types with infrequent and often weak GPX2 staining included sarcomas, lymphomas, high-grade serous ovarian carcinomas, prostatic adenocarcinomas, melanomas, mesotheliomas, and renal cell carcinomas." (PMID 42158439, 2026). "Compared to fibroblasts, prognostic genes were significantly up-regulated in 3 human melanoma cell lines, especially GPX2, DERL3, NDRG1, and DTL (p < 0.05)." (PMID 41409301, 2025). "GPX2 not only directly protects tumor cells from ROS invasion, but also weakens anti-tumor immune response by disrupting T cell functionality, jointly promoting the progression and immune escape of melanoma." (PMID 41409301, 2025). "The genes of HAMP, SLC7A5, CYBB, and IFNG were highly expressed in melanoma cell lines, while JDP2, TUBE1, PROM2, GPX2, FBXW7, and ARNTL were lowly expressed in melanoma cell lines." (PMID 35373463, 2022). "Expressions of GPX2, GPX4, GSR, and G6PD have been found to be elevated in melanomas and other cancers." (PMID 35326683, 2022). "GPX2 and GPX4 have been demonstrated to play a role in the resistance of melanoma to therapies." (PMID 35326683, 2022).
selenium deficiency (4 papers, 2012 to 2023). A nutritional deficiency disease resulting from inadequate selenium levels in the body, which can lead to impaired function of selenoproteins essential for antioxidant defense and thyroid hormone metabolism. "In mice, selenium deficiency has been previously demonstrated to increase expression of GPx2 in the gastrointestinal tract; however, this is the first study to investigate the effects of dietary selenium deficiency on foetal selenoprotein expression." (PMID 32210049, 2020). "One of these, miRNA-185, whose expression decreased under selenium deficiency, was confirmed to regulate expression of glutathione peroxidase 2 (GPx2) and selenophosphate synthetase 2 (SPS-2) genes." (PMID 29065468, 2017). "Selenium deficiency affects the expression of selenoenzymes such as GPx1, GPx2, and GPx4 and selenoproteins (i.e., Selenoproteins-P, SELENOP), which are involved in not only fetal reproductive development and the regulation of oxidative stress but also the overall DNA methylation pattern." (PMID 37233634, 2023).
asthma (3 papers, 2014 to 2024). "Meanwhile, there were five different genes that were consistently downregulated in ciliated cells following Tet1 loss and/or HDM treatment, including the asthma-associated genes Gstp1, Gstm1, and Gpx2." (PMID 35627266, 2022). "In nonallergic asthma, the smallest significance levels appeared for 5 SNPs (the GCLM −588C>T, GSR T>C, CAT −21A>T, CYBA −930A>G, and EPHX1 Y113H) in men and for 2 SNPs (the EPHX1 Y113H and GPX2 G>A) in women." (PMID 24895604, 2014).
colorectal adenocarcinoma (3 papers, 2021 to 2026). The most common type of colorectal carcinoma. "The aim of the present study was to investigate the prognostic relevance of Gpx-2 expression in patients with colorectal adenocarcinoma, with particular emphasis on its association with 5-year survival." (PMID 37834097, 2023). "GPX2 positivity was most seen in colorectal adenocarcinomas (97.9%) and adenomas (100%), non-invasive urothelial carcinomas (88.9-100%), pancreatico-biliary cancers (83.4-94.7%), Brenner tumors of the ovary (89.7%), gastro-esophageal adenocarcinomas (83.1-87.3%), and seminomas (85.6%)." (PMID 42158439, 2026). "The results of our cohort study indicate that in patients with colorectal adenocarcinoma, histological differentiation grade and Gpx-2 expression were identified as independent indicators significantly associated with 5-year survival as demonstrated with the use of a multivariate analysis." (PMID 37834097, 2023).
esophageal cancer (3 papers, 2007 to 2022). A primary or metastatic malignant neoplasm involving the esophagus. "As in breast, GPx2 loss in bladder and esophageal carcinomas led to disease progression and worse prognosis." (PMID 35193955, 2022).
non-small cell lung carcinoma (3 papers, 2023 to 2025). A group of at least three distinct histological types of lung cancer, including non-small cell squamous cell carcinoma, adenocarcinoma, and large cell carcinoma. "In contrast, GPx2 was confirmed as an oncogene that could promote malignant progression and cisplatin resistance in non-small cell lung carcinoma (NSCLC)." (PMID 37138031, 2023).
prostate intraepithelial neoplasia (3 papers, 2017 to 2023). A neoplastic proliferation of the epithelial cells that line the acini and the ducts of the prostate gland. "However, GPx2 was also observed to be down-regulated in prostatic intraepithelial neoplasia, indicating GPx2 may play a more complex role in tumorigenesis." (PMID 29108391, 2017).
urothelial carcinoma (3 papers, 2018 to 2026). A malignant neoplasm derived from the transitional epithelium of the urinary tract (urinary bladder, ureter, urethra, or renal pelvis). "Further, the expression level of Gpx2 was significantly higher in papillary or nodular hyperplasia (PNHP) and pure urothelial carcinoma (UC) lesions than in the normal epithelium of BBN + PEITC-treated rats." (PMID 29662611, 2018). "GPX2 expression gradually increased during progression from normal to papillary or nodular hyperplasia (PNHP) and urothelial carcinoma (UC) in a rat N-butyl-N-(4-hydroxybutyl) nitrosamine (BBN)-induced bladder carcinogenesis model." (PMID 29662611, 2018).
adenoma (2 papers, 2018 to 2026). A neoplasm arising from the epithelium. "GPX2 and TXNRD3 showed a higher expression and GPX3, SELENOP, SELENOS, and SEPHS2 exhibited a lower expression in the disease tissue from adenomas and both cancer groups (p-values from 0.023 to <0.001)." (PMID 30469315, 2018). "These included increasing down-regulation of GPX3, SELENOP, SELENOS, and SEPHS2 and up-regulation of GPX2, SELENOH, and TXNRD3, in groups of normal-matched tissues, adenomas, and adenomas with HGD." (PMID 30469315, 2018).
breast tumor (2 papers, 2022 to 2024). "Pair-wise mRNA expression correlation analysis in human breast tumors from TCGA cohort showed a positive correlation between ZMYND8 and antioxidant genes including NQO1, GPX2, GCLC, GCLM, TXNRD1, and SRXN1." (PMID 38488001, 2024). "GPX-1 and MRPL14 mRNAs are also depleted (>60%) from human breast tumor MCF-7 cells (GPX-2 is not expressed in MCF-7 cells)." (PMID 35104504, 2022).
colon adenocarcinoma (2 papers, 2021 to 2023). "It is worth noting that our study is the first to demonstrate the immunohistochemical expression of Gpx-2 in colon adenocarcinoma tissues in European populations." (PMID 37834097, 2023). "We also investigated the correlation between Gpx-2 protein expression and clinicopathological factors in patients with colon adenocarcinoma, e.g., a correlation between Gpx-2 expression and proliferating cell nuclear antigen (PCNA) expression." (PMID 37834097, 2023). "We can conclude that high expression of Gpx-2 is correlated with reduced survival of colon adenocarcinoma patients (log-rank, p < 0.001)." (PMID 37834097, 2023). "The present study used immunogold labelling to reveal the subcellular distribution of the Gpx-2 protein in colon adenocarcinoma samples." (PMID 37834097, 2023). "Results of our study demonstrated that expression of Gpx-2 in colon adenocarcinoma tissue was upregulated in comparison to that observed in the non-pathological tissue of the surgical margin." (PMID 37834097, 2023). "The multivariate analysis suggests that the grade of histological differentiation and immunohistochemical expression of Gpx-2 in colon adenocarcinoma tissue can be considered as an independent prognostic factor." (PMID 37834097, 2023). "Our preliminary report indicates that Gpx-2, a protein, is connected with reduced 5-year survival in colon adenocarcinoma patients." (PMID 37834097, 2023). "It is important to note that among our group of patients, 81% of colon adenocarcinoma samples displayed high levels of Gpx-2 protein expression, while only 19% exhibited low levels of immunoreactivity." (PMID 37834097, 2023). "Within the study cohort, 101 colon adenocarcinoma samples showed robust expression of the Gpx-2 protein, representing 80.80% of the cohort." (PMID 37834097, 2023). "Other miRNAs, including miR-185, can prevent human colon adenocarcinoma cells from sustaining oxidative damage by upregulating glutathione peroxidase 2 (GPX2)." (PMID 34235152, 2021). "We aimed to study the expression of Gpx-2 in colon adenocarcinomas through immunofluorescence." (PMID 37834097, 2023). "Hence, we investigated the immunohistochemical expression of Gpx-2 protein in colon adenocarcinoma samples derived from patients with colon adenocarcinoma who did not receive any form of treatment prior to the surgical procedure." (PMID 37834097, 2023). "Gpx-2 might be an important predictor for the prognosis of colon adenocarcinoma and a potential target for intervention and treatment of such patients." (PMID 37834097, 2023). "Our research aimed to investigate the expression of Gpx-2 protein in patients diagnosed with colon adenocarcinoma who had not received any treatment prior to surgery." (PMID 37834097, 2023).
fungal keratitis (2 papers, 2017 to 2023). "The average ratios of the expression levels of the Hmox1, Nos3, Hif1a, Sod2, Sod3, and Gpx2 genes increased more than 2-fold (p < 0.05) at day 1 p.i. in the fungal keratitis model, whereas the expression ratios of the Hif1an and Prdx6 genes decreased more than 2-fold (p < 0.05)." (PMID 28874754, 2017).
inflammatory bowel disease (2 papers, 2020 to 2021). A spectrum of small and large bowel inflammatory diseases of unknown etiology. "Progression of inflammatory bowel disease appeared to be determined by a quite complex mechanism of balance between pro-inflammatory redox-sensitive pathways, such as NLRP3 inflammasome and NF-κB, and the adaptive up-regulation of the antioxidant enzymes Mn-SOD and glutathione peroxidase 2 (GPX2)." (PMID 33573222, 2021).
lymph node metastases (2 papers, 2008 to 2025). "The gene with the second highest prognostic accuracy was GPX2; low expression of this gene was also associated with lymph node metastases." (PMID 18506145, 2008). "Univariate Cox analysis identified GPX2 protein expression, TNM stage, lymph node metastasis, and Lauren classification as prognostic risk factors for GC." (PMID 41145471, 2025).
oral cancer (2 papers, 2023). "Likewise, overexpression of an NRF2 target, GPX2, in a different mouse model of oral cancer results in M2 skewing and an increase in myeloid-derived suppressors but with a reduction in T-cell infiltration." (PMID 37716475, 2023). "Additionally, Serglycin (SRGN), a gene with apoptotic function was found to be down-regulated in oral cancer patients, and finally, GPX2, a gene responsible for detoxification and antioxidant activity was found to be up-regulated." (PMID 38234400, 2023).
thyroid cancer (2 papers, 2015 to 2020). "Genes related to cytoprotection and antioxidant response (e.g., Gsta3, Gstm1, Nqo1, Gpx2), as well as the H2O2-producing gene Aox1 that is usually decreased in thyroid cancers, were all downregulated in thyroids of KO mice, as found previously in other tissues." (PMID 32961913, 2020). "Glutathione peroxidase family showed variable gene expression: GPX1 and GPX2 expression analysis suggested minor increase in mRNA synthesis, GPX3, GPX5, and GPX7 expression was downregulated in thyroid cancers, whereas GPX4 expression did not change." (PMID 26664298, 2015).
adrenocortical cancer (1 paper, 2021). "Abnormal expression of GPX2 might facilitate tumorigenesis and result in poor progress in adrenocortical cancer, kidney papillary cell carcinoma, and uveal melanoma." (PMID 34867976, 2021).
allergic asthma (1 paper, 2014). A asthma with a basis in a pathological type I hypersensitivity reaction. "Moreover, the CAT −21A>T and GPX2 G>A gene polymorphisms had a strong antagonistic effect on the risk of allergic asthma in men." (PMID 24895604, 2014).
benign prostatic hyperplasia (1 paper, 2022). A non-cancerous nodular enlargement of the prostate gland. "Second, GPX2 was highly expressed in benign prostatic hyperplasia compared with PCa." (PMID 36312753, 2022).
brain tumor (1 paper, 2023). "In our study, gpx3 was highly expressed in brain tumor tissue and also showed gender differences in the same way that gpx2 did." (PMID 37761814, 2023).
cholestasis (1 paper, 2017). Impairment of the bile flow caused by obstruction within the liver, or outside the liver in the bile duct system. "After ANIT-induced cholestasis was treated with fenofibrate, the levels of Gsta2, Gsta4, Gstm3, and Gpx2 were significantly decreased (P < 0.01)." (PMID 28855630, 2017). "In our study, the expression levels of Gsta2, Gsta4, Gstm3 and Gpx2 were increased in the ANIT-induced cholestasis." (PMID 28855630, 2017).
colorectal adenoma (1 paper, 2013). An adenoma that arises from the colon or rectum. "More specifically, elevated glutathione peroxidase-2 (Gpx-2) expression has been detected in colorectal adenomas." (PMID 23861820, 2013).
dry eye (1 paper, 2023). "Mitochondrial genes such as MT-CYB or MT-CO2 were overexpressed, as were genes associated with oxidoreductase activity; SOD genes and GPX2 were up-regulated in patients with dry eye." (PMID 38254630, 2023).
gastric adenocarcinoma (1 paper, 2025). "The activation of the reactive oxygen species (ROS)-mediated KYNU-kyn-AhR signaling pathway, resulting from GPX2 knockdown, has been implicated in the progression and metastasis of gastric adenocarcinoma (GAC)." (PMID 41145471, 2025). "To further confirm GPX2 expression in DGC, we analyzed its levels in the gastric adenocarcinoma (STAD) cohort from The Cancer Genome Atlas (TCGA) and the Asian Cancer Research Group (ACRG), and the results revealed heightened increased GPX2 expression in GC." (PMID 41145471, 2025).